RNU7-160P (RNA, U7 small nuclear 160 pseudogene)
Gene: Small nuclear RNA gene on chromosome 14 (103,550,345 to 103,550,406, forward strand). Ensembl gene ENSG00000252469.
Homologues: Orthologues: macaque U7 (89% identical), pig U7 (84% identical). Paralogues in human: RNU7-52P (89% identical), RNU7-60P (87% identical), RNU7-11P (85% identical), RNU7-13P (85% identical), RNU7-2P (85% identical), RNU7-1 (84% identical), RNU7-24P (84% identical), RNU7-48P (84% identical), RNU7-56P (84% identical), RNU7-6P (84% identical), RNU7-124P (82% identical), RNU7-12P (82% identical), and 141 more.